RNU6-1321P (RNA, U6 small nuclear 1321, pseudogene)
Gene: Small nuclear RNA gene on chromosome X (41,570,923 to 41,571,029, reverse strand). Ensembl gene ENSG00000212207.
Homologues: Orthologues: chimpanzee U6 (100% identical), macaque U6 (93% identical). Paralogues in human: RNU6-21P (84% identical), RNU6-1158P (83% identical), RNU6-468P (83% identical), RNU6-1011P (82% identical), RNU6-166P (82% identical), RNU6-31P (82% identical), RNU6-38P (82% identical), RNU6-1189P (81% identical), RNU6-42P (81% identical), RNU6-517P (81% identical), RNU6-574P (81% identical), RNU6-630P (81% identical), and 1285 more.